KRAS (KRas proto-oncogene, GTPase)
Diseases named in the same sentence as KRAS in open-access papers (continued):
Sharing a sentence is not in itself a finding about the gene and the disease.
pancreatic cancer (continued). "Chronic pancreatitis and mutant Kirsten rat sarcoma viral oncogene homolog KRAS gene (Ki-ras2 Kirsten rat sarcoma viral oncogene homolog) are the most common entities involved in pancreatic carcinogenesis, with more than 90% of human pancreatic carcinomas carrying the KRAS gene mutation." (PMID 33255197, 2020). "However, we believe that our enrichment assay could be advantageous in improving the diagnosis of KRAS-mutated ctDNA and could be also used for the early detection of pancreatic cancer." (PMID 31383871, 2019). "In a phase 1/2 clinical trial, a mutant KRAS vaccine, designed to induce T-helper responses, seemed to induce immunologic response in a number of patients with resected pancreatic cancer, and it might be associated with improved long-term immune responses and long-term survival." (PMID 31540286, 2019). "Hyperinsulinemia is a risk factor for pancreatic cancer, but the function of insulin in carcinogenesis is unclear, so this study aimed to elucidate the carcinogenic effects of insulin and the synergistic effect with the KRAS mutation in the early stage of pancreatic cancer." (PMID 30838710, 2019). "In this paper, we demonstrate the association of both KRAS mutation in the pancreas and obesity with the increased loss of NK cell function at the pre-malignant stage of pancreatic tumorigenesis, likely paving the road for the establishment, invasion, and metastasis of pancreatic tumors." (PMID 29977235, 2018). "Once again, with more than 94% Pancreatic cancer patients carrying KRAS mutation and RAS genes (KRAS, NRAS, and HRAS) were observed to interact with each other through their mutations status and gene expression, it is highly expected that RAS genes could be highly associated with survival outcome." (PMID 30517129, 2018). "The ability to use the extremely high KRAS mutation frequency in pancreatic cancer provided us with an important control to directly assess technical feasibility of cfDNA based molecular profiling of metastatic cancer patients where access to tumor tissue may problematic." (PMID 29137355, 2017). "We applied a KRAS amplicon-based deep sequencing strategy combined with analytical pipeline specifically designed for the detection of low-abundance mutations to screen plasma samples of 437 pancreatic cancer cases, 141 chronic pancreatitis subjects, and 394 healthy controls." (PMID 27705932, 2016). "Whether the limited sensitivity and specificity observed in our series of KRAS mutations in plasma cfDNA as biomarkers for pancreatic cancer detection are attributable to methodological limitations or to the biology of cfDNA should be further assessed in large case-control series." (PMID 27705932, 2016). "KRAS mutant allele-specific imbalance has been reported to correlate with progression to undifferentiated carcinoma of the pancreas, and expression of granulocyte/macrophage colony stimulating factor (GM-CSF) to correlate with KRAS mutations in pancreatic tumors." (PMID 26366343, 2015). "Although KRAS mutations act as a key event in pancreatic carcinogenesis, targeting upstream signals that modulate KRAS activity may be a promising future approach for treating pancreatic cancer." (PMID 25905463, 2015). "KRAS mutations are the first known genetic alterations known to occur sporadically in normal pancreatic tissue, chronic pancreatitis, and smokers; moreover, they are detected in approximately 30% of early pancreatic neoplasms and close to 100% of advanced PDAC lesions." (PMID 24624093, 2014). "Additionally, underexpression of RBM5 and overexpression of KRAS in pancreatic cancer has a close association with metastasis and invasion-related clinicopathological features, suggesting their collaboration in prompting tumor ability of invasion and metastasis." (PMID 23425895, 2013). "However, inhibitors of EGFR still show efficacy in some KRAS mutated pancreatic cancer cell lines." (PMID 22367239, 2013).
pancreatic cancer (continued). "The ability to characterise CTCs downstream of ISET filtration in a flexible manner may facilitate measurement of predictive biomarkers allowing stratification of pancreatic cancer patients most likely to benefit from novel targeted therapies, for example, KRAS and EGFR mutation analysis." (PMID 22187035, 2012). "This review synthesizes evidence from basic research and clinical translation to provide a theoretical foundation and practical guidance for the precision treatment of KRAS-mutant pancreatic cancer." (PMID 41942368, 2026). "Recent breakthroughs with next-generation KRAS inhibitors have transformed the therapeutic landscape for pancreatic cancer." (PMID 41942368, 2026). "KRAS (G12V) mutations have been linked to aggressive tumor biology in patients with colorectal and pancreatic cancer, often correlating with shorter overall survival compared with other subtypes of KRAS." (PMID 40491286, 2026). "Here, we determined the effects of PCAIs on the viability and downstream mediators of KRAS on pancreatic cancer-derived PANC-1 and MIAPaCa-2 cells." (PMID 42233520, 2026). "Combining FTIs with KRAS-G12C or KRAS-G12D inhibitors has also shown synergistic effects, potentially breaking down resistance mechanisms in pancreatic cancer." (PMID 41550359, 2026). "A recent study demonstrated complete regression of KRAS-driven pancreatic cancer upon systemic ablation up- and downstream signaling proteins EGFR and C-RAF." (PMID 42030284, 2026). "We next directly examined the roles of LZTR1 and PPP1R2/PP1C in regulating KRAS stability across the tested adenocarcinoma lines, as well as in the pancreatic cancer line Mia PaCa-2." (PMID 41542462, 2026). "The authors found that administration of the KRAS inhibitors sotorasib or MRTX1133 to pancreatic cancer cell lines upregulated STAT3 phosphorylation and reactivated ERK through a feedback reaction." (PMID 39400496, 2025). "Preclinical studies demonstrate that in a KRAS G12D-mutant AsPC-1 human pancreatic cancer xenograft model (nude mice), intravenous administration of HRS-4642 significantly inhibits tumor growth in a dose-dependent manner with favorable tolerability." (PMID 40689200, 2025). "Inhibition of lactate production in pancreatic tumors via glycolysis or mutant-KRAS inhibition reshaped the TME, thereby increasing their sensitivity to immune checkpoint blockade (ICB) therapy." (PMID 39883522, 2025). "For example, KRAS in pancreatic cancer and BRAF in melanoma occur before cell invasion in benign and early lesions." (PMID 40397908, 2025). "Oxidative stress interacts with mutant KRAS, collaboratively promoting the initiation and progression of pancreatic cancer." (PMID 40918147, 2025). "To this extent, we highlight the necessity to include studies of KRAS allelic frequencies in the design of future therapeutic strategies against pancreatic cancer." (PMID 40227826, 2025). "In a study using exosomes to deliver small interfering RNAs (siRNAs) targeting KRAS in pancreatic cancer, researchers found that the exosomes penetrated deeply into the tumor core, significantly suppressing tumor growth." (PMID 40843170, 2025). "As a result, the National Cancer Institute (NCI) has identified KRAS targeting as one of the key priorities for pancreatic cancer research over the next decade." (PMID 40149381, 2025). "After the treatment with siRNA-LNPs, significant reduction in KRAS mRNA expression was observed in CFPAC-1 pancreatic cancer cells." (PMID 39820726, 2025).
pancreatic cancer (continued). "This study demonstrates the repressive role of WT KRAS during pancreatic tumorigenesis and highlights the critical impact of the presence of WT KRAS in both tumor progression and therapeutic response in pancreatic cancer." (PMID 39412982, 2025). "It has demonstrated promising clinical activity in phase I/II trials across multiple malignancies, including non-small cell lung cancer, advanced melanoma, hormone receptor-positive breast cancer, and KRAS-mutant colorectal and pancreatic cancers." (PMID 41208974, 2025). "In pancreatic carcinogenesis, chronic ER stress leads to an inflammatory state that, along with KRAS mutations, induces AGR2 expression and contributes to pancreatic cancer development." (PMID 40459063, 2025). "Non-invasive diagnostic approaches hold promise for more efficient cancer surveillance, including liquid biopsy technologies targeting KRAS mutations, exosome markers, and VOC breath analysis for efficient pancreatic cancer (PC) detection." (PMID 41009762, 2025). "There is increasing evidence that metabolism in pancreatic cancer cells is controlled by the oncogenic KRAS, which activates several downstream signalling pathways." (PMID 40567499, 2025). "Consistent with observations in mouse PDAC, quantitative analysis of nuclear CSA revealed that nuclei from human mutant KRAS pancreatic tumor tissue were reduced in size compared with adjacent normal or KRAS WT PDACs." (PMID 40493403, 2025). "This metabolic reprogramming of pancreatic cancer is mainly mediated by mutant KRAS (KRAS∗), and that oncogenic KRAS∗ is the signature genetic event for pancreatic cancer progression." (PMID 40247913, 2025). "Since knockout of SIRT5 has been reported to promote the KRASG12D-driven PDAC progression in the KPC mouse model, we mainly focused our study on the regulation of SIRT3 by KRASG12D and its potential role in KRAS-driven pancreatic cancer development." (PMID 41391757, 2025). "Allelic imbalances at the KRAS locus have previously been reported in pancreatic ductal adenocarcinoma (PDAC), the most common type of pancreatic cancer, and were associated with early tumor progression." (PMID 39412982, 2025). "Upregulation of GATA6 enhanced chemosensitivity of pancreatic cancer cells, and KRAS/ERK inhibitors synergized with chemotherapy in a GATA6-dependent manner." (PMID 41329526, 2025). "In the field of pancreatic cancer, which has the largest number of reports, most studies have used MRD testing based on ctDNA analysis of KRAS mutations." (PMID 39920551, 2025). "In pancreatic cancer, contact with KRAS-mutant cells led to higher expression of M2 markers and increased pro-tumor effects of macrophages." (PMID 40524071, 2025). "Our previous study provides compelling evidence that RASON, a novel protein we discovered in pancreatic cancer, functions as a stabilizer of KRAS activity." (PMID 40128846, 2025). "Research indicates that recurrent mutant genes in pancreatic cancer are predominantly enriched in signaling pathways such as KRAS, TGF‐β, WNT, and NOTCH, which is consistent with our findings." (PMID 41176774, 2025). "The exact role of SIRT3 in pancreatic cancer tumorigenesis in vivo and the relation between KRAS and SIRT3 remain to be investigated." (PMID 41391757, 2025). "A multi-omics analysis strategy has revealed compensatory activation of the CDK kinase network in KRAS-mutant pancreatic cancer." (PMID 41463025, 2025).
pancreatic cancer (continued). "The Chinese Society of Clinical Oncology (CSCO) Pancreatic Cancer Guidelines recommend nimotuzumab plus gemcitabine as first-line and beyond therapy for advanced KRAS wild-type PDAC." (PMID 40689200, 2025). "Targeting oncogenic mutations like KRAS and GNAS offers a potential avenue for preventing pancreatic cancer development, but ongoing clinical trials are necessary to determine prophylactic efficiency." (PMID 40074443, 2025). "KRAS is pivotal in the initiation, progressiogn, and local and distant invasion of pancreatic cancer." (PMID 40868269, 2025). "It efficiently inhibited oncogenic KRAS expression in a panel of human lung, colon, and pancreatic cancer cell lines both in vitro and in vivo." (PMID 40650182, 2025). "Pancreatic cancer shows 83% of KRAS and 2% of APC, whereas gallbladder cancer shows frequencies of 10% and 3%, respectively." (PMID 40916582, 2025). "Screening mutant KRAS-reactive T cells from the peripheral blood of pancreatic cancer patients represents a convenient and effective method to identify mutant KRAS-reactive TCRs." (PMID 39846249, 2025). "Pancreatic cancer cells have been experimentally confirmed to release KRAS–G12D through the autophagy‐lysosome pathway, a process involving dynamic fusion of autophagosome and multivesicular body membranes." (PMID 40919133, 2025). "In early studies, it was postulated that aberrant hedgehog signaling in pancreatic cancer was the result of constitutive NF-κB signaling driven by oncogenic KRAS expression." (PMID 39941724, 2025). "Our work offers a mechanistic explanation for the relative absence of KRASQ61L in PDAC and contributes to our understanding of KRAS allele-specific vulnerabilities, which can inform future therapeutic strategies targeting KRAS-driven pancreatic cancer." (PMID 40951926, 2025). "This included GLUT1 and HK2, which have been previously shown to significantly increase aerobic glycolysis in pancreatic cancer and are induced by KRAS and STAT3, respectively." (PMID 40647442, 2025). "In a mouse model of pancreatic cancer, mutant KRAS was shown to enhance GM-CSF expression via the MAPK pathway, leading to the recruitment of Gr-1+CD11b+ myeloid cells." (PMID 40333779, 2025). "Screening for KRAS G12V–reactive T cells from PBMCs of HLA-A*11:01–expressing patients with pancreatic cancer." (PMID 39846249, 2025). "KRAS is central in metabolic regulation in pancreatic cancer models, while HRAS and NRAS exhibit distinct functions in other cancer types." (PMID 40906088, 2025). "In this study, we used patient pancreatic cancer organoids to validate the recognition and killing by our identified HLA-A*11:01–restricted KRAS G12V–reactive TCR–transduced T cells." (PMID 39846249, 2025). "For pancreatic cancer cell lines, we have established two CDX models: one with deletion of the SMAD4 gene and the other from a KRAS mutation cell line." (PMID 40190550, 2025). "Studies have demonstrated that ROS play a crucial role in cell transformation induced by the mutant oncogenic KRAS and the proliferation of pancreatic tumors." (PMID 40918147, 2025). "For instance, a Phase I trial (NCT03608631) is testing MSC‐derived exosomes delivering KRAS‐G12D siRNA in pancreatic cancer." (PMID 41050664, 2025). "Other new covalent KRAS G12C inhibitors are recently demonstrating higher activity with an ORR > 40% in pancreatic cancer." (PMID 40124650, 2025). "In pancreatic cancer, ferroptotic cells release KRAS G12D, which polarizes macrophages to an M2 phenotype through STAT3 signaling, promoting immune suppression and tumor progression." (PMID 40919133, 2025). "In colon cancer, KRAS induced the conversion of helper T cells into Tregs, a finding later confirmed in pancreatic cancer." (PMID 40524071, 2025).
pancreatic cancer (continued). "For instance, KRAS overactivation in pancreatic cancer increases interleukin-6 (IL-6) secretion, which facilitates tumour development via the JAK1/STAT3 pathway and triggers reactive oxygen species generation and oxidative stress responses." (PMID 39820726, 2025). "It exhibited high selectivity in inhibiting the growth of KRAS-G12D-mutant cell lines and demonstrated robust efficacy against KRAS-G12D-mutant human pancreatic cancer and CRC models." (PMID 40361439, 2025). "Its ability to reduce the stemness led to the apoptosis of colorectal cancer HCT116 and HT29 cells and impaired formation of tumor spheres, while in a few lung, colon, and pancreatic cancer cell lines, it diminished oncogenic KRAS expression." (PMID 40650182, 2025). "We found that CaaX‐1 has a different impact on KRas signaling and KRas regulators in the two pancreatic cancer cell lines tested, suggesting specificity with respect to the KRas‐mutated PANC‐1 cells." (PMID 40270247, 2025). "For example, MALAT1 and NUTF2P3-01 were both found to be overexpressed in pancreatic cancer, and their knockdown led to a reduction in KRAS protein level." (PMID 40427100, 2025). "In the genetically engineered KRAS-G12D-driven KPC-mouse model for spontaneous pancreatic cancer, deletion of APLP2 significantly prolonged survival and reduced metastasis." (PMID 41362608, 2025). "We thus analyzed the effects of these mutations on KRAS activation status using MIA-Paca2, a pancreatic cancer-derived cell line." (PMID 40286847, 2025). "In this work, we utilized conjugated DNA origami tubules, known as Do‐Cy, for selectively imaging KRAS mutant pancreatic cancer cells." (PMID 39951277, 2025). "Previous studies have reported that altered KRAS gene dosage drives progression and metastasis in pancreatic cancer." (PMID 39412982, 2025). "In pancreatic cancer, radiomics features by [18F]FDG PET/CT can predict some genetic mutations such as KRAS and SMAD4." (PMID 40192792, 2025). "The aim of this study was to determine the cytotoxicity of ECT using BLM or CDDP and to evaluate the interactions of ECT with the targeted drug sotorasib in KRAS G12C-mutated MIA PaCa-2 and KRAS G12D-mutated PANC-1 pancreatic cancer cell lines." (PMID 40806294, 2025). "Using in vivo mouse modeling of pancreatic cancer, we demonstrated that WT KRAS restrains the oncogenic impact of mutant KRAS and dramatically impacts both KRAS-mediated tumorigenesis and therapeutic response." (PMID 39412982, 2025). "In the 2000s, research shifted toward targeted therapies, focusing on KRAS, the most prevalent RAS variant in pancreatic cancer." (PMID 40906088, 2025). "Next Generation Sequencing methods (NGS) have made it possible to assess KRAS allelic frequencies in many cohorts of pancreatic tumors." (PMID 40227826, 2025). "Here, we report that oncogenic KRAS-activated ERK signaling suppresses GATA6 transcription in pancreatic cancers." (PMID 41329526, 2025). "Since TBK1 is a major downstream modulator of oncogenic Ras and a possible therapeutic target, this signaling pathway is especially important in KRAS-driven malignancies like pancreatic cancer." (PMID 40483365, 2025). "Feature Selection (FS) technique and Qiagen's Ingenuity Pathway Analysis (IPA) were used to combine DNA‐Seq and RNA‐Seq data from mutant and wild‐type (WT) KRAS colon and pancreatic tumor samples." (PMID 40013338, 2025). "Inhibiting Plk1 with BI2356 or volasertib significantly increased ROS levels in KRAS-mutant colon cancer, pancreatic cancer, and cervical cancer cells, while pre-treatment with a ROS scavenger partially reversed volasertib-induced apoptosis." (PMID 40166466, 2025). "DNA origami‐cyanine (Do‐Cy) nanocomplexes are synthesized to selectively image KRAS‐mutant pancreatic cancer cells in the highly desmoplastic tumors." (PMID 39951277, 2025). "Lipid metabolism is influenced by oncogenic KRAS in pancreatic cancer, promoting studies into lipidomic profiling in pancreatic cancer diagnosis." (PMID 40363817, 2025).